HBB (hemoglobin subunit beta)
Diseases named in the same sentence as HBB in open-access papers (continued):
Sharing a sentence is not in itself a finding about the gene and the disease.
sickle cell disease (continued). "Sickle cell disease (SCD) is a disorder characterized by the inheritance of a single base substitution in the first exon of the β-globin gene (HBB)." (PMID 38027257, 2023). "β-hemoglobinopathies like sickle cell disease (SCD) and β-thalassemia are characterized by differing mutations in the hemoglobin subunit beta gene (HBB)." (PMID 36250099, 2022). "Sickle cell disease (SCD) is the most widespread monogenic disease worldwide with significant morbidity and mortality, associated with the HBB mutation, rs334 (Glu6→Val; GAG→GTG)." (PMID 34204365, 2021). "Sickle cell disease (SCD) is an inherited blood disorder caused by the point mutation 69A>T in the hemoglobin beta chain gene (HBB), encoding the beta globin subunit of hemoglobin-A (HbA) in normal red blood cells (RBCs)." (PMID 28610635, 2017). "Two studies, one in a normal population and the other in sickle cell anemia, showed that BCL11A, the HBS1l-MYB interval and variants in HBB were associated with HbA2 level." (PMID 26215470, 2015). "Comparable marker contributions to baseline HbF were reported for BCL11A and HBB in adult sickle cell disease." (PMID 23409025, 2013). "A point mutation in the adult beta globin gene (HBB) (c.20A>T, p.Glu7Val) results in the production of an abnormal hemoglobin (Hb S), which polymerizes when deoxygenated and leads to the classical clinical phenotype seen in sickle cell disease (SCD)." (PMID 38535125, 2024). "Sickle cell Anaemia (SCA) is one of the most prevalent monogenic disorders worldwide, caused by a single transverse point mutation (GAG>GTG) in the sixth codon of the beta-globin (HBB) gene." (PMID 36605051, 2022). "SCD refers to the full range of potential genotypes involving the mutated HBB gene, not to be confused with sickle cell anemia which refers specifically to being homozygous for this mutated HBB gene." (PMID 36250099, 2022). "For HBB targeting, we used a previously validated and highly effective sgRNA and ssODN combination (approximately 60% NHEJ and 20% HDR) designed to introduce the causative mutation involved in sickle cell disease." (PMID 33661998, 2021). "Only three genetic loci have been validated as strongly associated with higher HbF in sickle cell disease: the 5′ beta globin locus (HBB), although not the sickle mutation; the BCL11A repressor of HbF; and the HS1L-MYB intergenic region." (PMID 23409025, 2013). "Both diseases could be cured if HBG, a gene closely related to HBB, could be upregulated such that it could either replace the missing γ-globin protein (in β-thalassemia) or counteract the dysfunctional γ-globin protein (in sickle cell disease)." (PMID 26694713, 2015). "A systematic characterization of HBB gene and other Hemoglobin genes in Kuwaiti Thalassemia and sickle cell anemia population might further reveal rare ancestry-specific variants of Hemoglobin that are useful in developing prenatal and carrier genetic tests in risk families." (PMID 24896259, 2014). "Sickle cell disease (SCD) is characterized by vaso-occlusion and chronic hemolysis, brought about by a qualitative defect in erythroid β-globin (HBB) expression." (PMID 40362693, 2025). "For example, the African specific (∼91% of the carriers) HBB c.20A > T (rs334) variant, is a known recessive pathogenic variant which causes sickle-cell disease (MIM:603903), but it is present in four African individuals (who could have sickle-cell disease) in a homozygous state in gnomAD." (PMID 32231685, 2020). "This novel therapy could be provided as a medication to fix defected genes, such as the hemoglobin subunit beta (HBB) gene, which is known to be defected in β-TM and sickle cell disease." (PMID 39802567, 2024). "However, it is worth noting that detailed and in-depth studies of the HBB gene in AA tissues are still lacking, and it is well-established that HBB gene mutations are associated with several severe hemoglobinopathies, such as sickle cell anemia and β-thalassemia." (PMID 36341412, 2022).
sickle cell disease (continued). "Common HbF BCL11A enhancer haplotypes in patients with African origin and AI sickle cell anemia appeared to have similar effects on HbF but did not explain the differences in HbF among the HBB haplotypes." (PMID 26215470, 2015).
thalassemia (86 papers, 2010 to 2026). An inherited blood disorder characterized by a decreased synthesis of one of the polypeptide chains that form hemoglobin. "By contrast, a thalassaemia-causing HBB LoF mutation (rs11549407-A) and splice site variant (rs33915217-G) were most prevalent in NFE and SAS." (PMID 40770095, 2025). "The β-globin gene HBB, in which pathogenic variants cause β-thalassemia, is sandwiched between olfactory receptor gene clusters, and β-globin deletions that cause thalassemia have been known to extend to these olfactory genes." (PMID 40306283, 2025). "In this study, carriers of the HBB: c.-23A>G mutation were identified from a cohort of 192,720 individuals who underwent thalassemia gene testing in the Gannan region." (PMID 41244801, 2025). "According to the Database of Human Hemoglobin Variants and Thalassemia Mutations, all individuals with heterozygous mutations in HBB c.180G>C, c.341T>A, c.68A>C, and c.68A>G present normally." (PMID 38660679, 2024). "Among the 17 thalassemia children with mutations in their HBB gene, 10 were males and seven were females." (PMID 39176330, 2024). "Although we excluded HBA1, HBA2, and HBB genes causing thalassemia and hemoglobinopathies, the carrier rate of at least one screened disorder was still as high as 14.7% (241/1642) in our cohort." (PMID 38167091, 2024). "Molecular analysis is the only definitive way to diagnose heterozygous thalassemia and can help qualify which HBB variant family’s harbor." (PMID 39062234, 2024). "One gene–phenotype association was shared between EUR and SAS, which was the hemoglobin subunit beta (HBB)–D56 thalassemia baseline association." (PMID 39261665, 2024). "Correction of HBB gene mutations in β‐thalassemia using gene editing contributes to the restoration of functional HBB gene expression." (PMID 39081515, 2024). "Here, we investigated the potential of CRISPR/GC mechanisms to restore HBB-4142 and other genetic mutations associated with thalassemia in the coding regions of the HBB gene." (PMID 39872888, 2023). "These three HBB variants were also reported in thalassemia patients and carriers of Greek and other Mediterranean Populations29." (PMID 37580329, 2023). "A long-read sequencing-based approach was first used in prenatal diagnosis of thalassemia in 2022, which additionally identified α-globin triplicates in two fetuses with the heterozygous HBB c.316-197C>T variant." (PMID 37529778, 2023). "The patient had a pathogenic variant in the HBB gene, considering the minor thalassemia status of the patient (NM_000518; c.93-21G > A)." (PMID 37038193, 2023). "The current study has also reported the presence of few HBB variants which were commonly present in both thalassemia patients and carriers." (PMID 37580329, 2023). "It is therefore suggested that the pathogenic HBB variants, identified during present study, can be employed for the diagnosis, carrier screening, and planning therapy of thalassemia." (PMID 37580329, 2023). "The SMRT method developed in this study focused on detection of variants in HBA1, HBA2, and HBB genes, which consisted the vast majority of thalassemia variants." (PMID 34690349, 2022). "Group I included four patients with 6 α-globin genes and a mutation in the HBB gene, this mutation was β0-thalassemia (two patients), severe β+-thalassemia (one patient), and mild β+-thalassemia (one patient)." (PMID 35402459, 2022). "F3 and sickle cell variant (HBB rs334) are associated with higher d-dimer levels in Blacks and thalassemia, iron overload, or high iron (HFE) mutations are associated with elevated ferritin levels in Asian/Indians." (PMID 35287602, 2022). "All had a mutation in the HBB gene (β0-thalassemia, β+-thalassemia severe, and β+-thalassemia mild)." (PMID 35402459, 2022). "The ß-hemoglobinopathies Sickle Cell Disease (SCD) and ß-thalassemia are genetic blood diseases characterized by defective or deficient adult ß-globin (HBB)." (PMID 30645582, 2019).
thalassemia (continued). "CRISPR/Cas9 technology with the combination of the piggyBac transposon has efficiently corrected the HBB mutations in iPSCs obtained from thalassemia patients." (PMID 31687377, 2019). "HBB:c.316-197C > T, HBB:c.126_129delCTTT and HBB:c.52A > T were the top three frequent β-thalassemia mutations and their percentage was significantly different in various provinces." (PMID 31113390, 2019). "In the state of Rio de Janeiro we identified one rare HBB mutation: HBB:c.75T>A [codon 24 (T>A)], a variant that leads to mild Sβ+ thalassemia." (PMID 31830127, 2019). "This approach also allowed us to describe the most common HBB mutations in patients classified as Sβ0 thalassemia and Sβ+ thalassemia." (PMID 31830127, 2019). "Worldwide, 80 to 90 million people carry the thalassemia allele in HBB gene." (PMID 38499809, 2024). "Furthermore, a 52-year-old woman who carried HBB p.F42fs variant and who suffered from a lacunar stroke in the motor area with thalassemia." (PMID 36580209, 2023). "The Hemoglobin Subunit Beta (HBB) gene is responsible for the arousal of β654-thalassaemia, so by the deletion of the HBB IVS2-654 site of mutation, the symptoms of this disease were alleviated and provided an opportunity for further enhancing the efficiency and performance in future studies." (PMID 36429042, 2022). "Molecular defects in β°-thalassemia could either be a point mutation in the HBB gene that completely disrupts its expression or a rare gene deletion that causes absent synthesis of the β-globin chain." (PMID 36533237, 2022). "Long-range PCR and long-molecule sequencing on the PacBio Sequel II platform utilized in this study could cover the entire HBA1, HBA2 and HBB genes, enabling the diagnosis of most of the common and rare types of thalassemia variants." (PMID 35701592, 2022). "A total of 22 HBB gene thalassemia variants were identified: 10 null variants leading to complete impairment of β-globin synthesis (β0); 4 with severe reduction in β-globin synthesis (β+); 5 with mild (β++); and 3 variants with very mild (so-called silent) reduction in β-chain synthesis (βsil)." (PMID 35336809, 2022). "Thalassemia may be caused by more than 200 different point mutations and, rarely, deletions in the HBB gene." (PMID 31687377, 2019). "Furthermore, borderline HbA2 values may occur due to mild/silent HBB mutations and co-inherited β-thalassemia and α- or δ-thalassemia." (PMID 39062234, 2024). "Thus far, more than 350 HBB mutations have been associated with thalassemia." (PMID 36645044, 2023). "We found that the HBB −28(A>G) mutation not only disturbed the transcription of HBB, but also decreased the expression of HBG, which may further aggravate the thalassemia phenotype and partially explain the more severe clinical outcome of β-thalassemia patients with the HBB −28(A>G) mutation." (PMID 33193694, 2020). "Moreover, this study demonstrated the feasibility and usefulness of cost-effective HRM approach in resource limited settings which can be followed in other countries of thalassemia-belt for detection of HBB gene mutations and confirmation of the carrier status." (PMID 31941534, 2020). "α‐Thalassemia and β‐thalassemia are two main types of thalassemia, which are caused by variants of HBA1 (OMIM 141800)/HBA2 (OMIM 141850) and HBB (OMIM 141900) genes." (PMID 41532136, 2026). "In this cohort, the prevalence of thalassemia, caused by pathogenic variants in HBA1/HBA2 and HBB, was 1/13, which aligns with previously reported findings." (PMID 40421383, 2025). "For instance, mutations in the HBB and HBA2 genes are linked to thalassemia, while ATP7B mutations cause Wilson’s disease." (PMID 40136557, 2025).
thalassemia (continued). "For example, the HBB and HBA2 genes are associated with thalassemia, the ATP7B gene is linked to Wilson’s disease, and a specific set of genes is related to hepatocellular carcinoma." (PMID 40136557, 2025). "We observed that 23.8% of individuals were carriers of thalassemia and hemoglobinopathies (HBB, HBA1, and HBA2), followed by 7.7% who were carries of G6PD deficiency." (PMID 38167091, 2024). "Heterozygous deletion of HBB exon 1-3 was verified using multiplex ligation-dependent probe amplification, whereas the remaining rare thalassemia genotypes were verified using Sanger sequencing." (PMID 38660679, 2024). "HBB p.K18* variant was detected in a 63-year-old man who suffered from hypertensive thalamic ICH and thalassemia (low hemoglobin)." (PMID 36580209, 2023). "The three HBB variants (c.315+74T>G, c.316-185C>T, and c.315+16G>C) detected by NGS were confirmed by Sanger sequencing in two thalassemia patients." (PMID 37580329, 2023). "The genotypes of thalassemia are region-specific, and 23 most common variants in HBA and HBB genes are routinely screened by PCR in diagnostic laboratories for thalassemia testing in China." (PMID 36685902, 2022). "At present, the detection range of the reagents we used only included 2062 variant sites related to thalassemia on the HBA1/2 and HBB genes." (PMID 34690349, 2022). "α- and β-Thalassemia are the most common forms of thalassemia, resulting from mutations in the α- and β-globin gene clusters (HBA1, HBA2, and HBB) on chromosome 16 and chromosome 11, respectively." (PMID 35783323, 2022). "We report the haematological parameters and molecular characterization of beta zero (β°) South East Asia (SEA) deletion in the HBB gene cluster with unusually high levels of Hb F compared to a classical heterozygous beta zero (β°)-thalassaemia." (PMID 36533237, 2022). "α-Thalassemia (α-thal) and β-thalassemia (β-thal) are two main types of thalassemia caused by mutations in the HBA1/2 and HBB genes respectively, which result in abnormal α- and β-globin synthesis and defective hemoglobin structure." (PMID 35701592, 2022). "The thalassaemia phenotype group describes the allele phenotype and includes HBA1 and HBA2 variants (α+/α0 and α+; total: 146 SNVs) and HBB variants (β0, β0/β+, β+, β++ (silent) and β++; total: 289 SNVs)." (PMID 36453528, 2022). "In our case, the combination of a silent HBB mutation CAP+1 (A>C) with β0 codon 5 [‐CT] mutation was reported for the first time, and it led to transfusion‐dependent thalassemia in the patient." (PMID 33491330, 2021). "Consistent with the family history of thalassemia (mother is a β-thalassemia carrier), a maternal pathogenic LOF mutation in HBB (c.126_129delCTTT, p.Phe42Leufs) was identified in Sib-3." (PMID 34356069, 2021). "As a result, thalassemia patients in the Mediterranean region have a high ratio of Codon 39 (C→T) and IVS‐I‐110 (G→A) mutation in HBB, which are the most frequent gene in Tunisia and Algeria (Anwar, Khyatti, & Hemminki, 2014)." (PMID 30968607, 2019). "Thalassemias are caused by mutations in the α (HBA1/HBA2) and β globin (HBB) genes and are usually inherited in an autosomal recessive manner." (PMID 33072976, 2019). "In mild thalassemia, a point mutation in the canonical poly (A) signal (AAUAAA) of the HBB gene causes a larger transcript to be produced." (PMID 26938874, 2016). "With this novel large deletion found in the HBB gene in China, we expand the genotype spectrum of β-thalassemia and show the advantages of long-read sequencing (LRS) for comprehensive and precise detection of thalassemia variants." (PMID 37521358, 2023). "The findings manifest a lower frequency of HBB mutation than CYP21A2 mutations in the Turkish Cypriot population rising in Northern Cyprus, which can be the result of the premarital screening program for Thalassemia that started in 1984." (PMID 37895316, 2023).